S100A4 (S100 calcium binding protein A4)
Diseases named in the same sentence as S100A4 in open-access papers (continued):
Sharing a sentence is not in itself a finding about the gene and the disease.
hepatocellular carcinoma (23 papers, 2017 to 2025). A malignant tumor that arises from hepatocytes. "In human patients and mouse models of hepatocellular carcinoma (HCC), high S100A4 expression positively associates with liver fibrosis and HCC grade and severity." (PMID 40078995, 2025). "S100A4 acted synergically with the extracellular matrix in the progression of hepatocellular carcinoma by affecting the stemness of cancer cells." (PMID 35214097, 2022). "The upregulation of PLAUR, S100A4, S100A6, and FGFR1 in mature B cells was involved in disease‐associated cellular migration and tissue invasion, which may influence hepatocellular carcinoma with persistent liver injury." (PMID 41190282, 2025). "Compared to NTA-MSCs, TA-MSCs from gastric cancer, lung cancer, pancreatic cancer and hepatocellular carcinoma (HCC) exhibit a notable elevation in cytokines like IL-6, IL-8 and TGF-β, along with genes including MMP1, S100A4, GREM1, and LOXL2, all of which are associated with tumorigenesis." (PMID 40676710, 2025). "Using the top three as examples: RASA1 was shown to be involved in the development of some sarcomas, CDK signaling was found to be a potential therapeutic target in hepatocellular carcinoma, and S100A4 was shown to maintain cancer-initiating cells in head and neck cancers." (PMID 37200395, 2023). "In addition, ectopic overexpression of S100A4 led to upregulation of oncogenic microRNA (miR)-155 expression in hepatocellular carcinoma cells, and an miR-155 inhibitor significantly attenuated the invasion-promoting effects of S100A4." (PMID 29342841, 2018). "Additionally, exosomal S100A4 plays a key role in hepatocellular carcinoma metastasis, by activating STAT3 phosphorylation and upregulating osteopontin expression, as well as inducing immunosuppression and non-small cell lung cancer development through STAT3 activation." (PMID 41002392, 2025). "In hepatocellular carcinoma (HCC) which is associated with chronic inflammation and fibrosis, galectin-1 deficiency with increased osteopontin and S100A4 expressions could amplify inflammatory processes, thereby exacerbating the liver injury and fibrosis in a mouse model of HCC." (PMID 36873388, 2023). "miR-187-3p is reported to post-transcriptionally regulate S100A4 and S100A4-mediated metastasis in hepatocellular carcinoma (HCC)." (PMID 28423501, 2017). "S100A4 is overexpressed in a variety of cancer entities like CRC, non-small cell lung, breast, oesophageal, gastric and hepatocellular cancers." (PMID 28423501, 2017). "For instance, miR-187-3p by targeting S100A4 could inhibit the metastasis and epithelial-mesenchymal transition (EMT) of hepatocellular carcinoma." (PMID 35317077, 2022).
bladder cancer (22 papers, 2008 to 2024). "S100A4 expression has proved to be a risk factor for muscle invasion in bladder cancer and found to increase the muscle invasion of bladder cancer in the early stages via MMP-14 expression." (PMID 29069865, 2017). "S100A4 induces the development of metastatic phenotype in rodent models of bladder cancer and its expression has been strongly associated with the development of bladder cancer metastases and poor survival of human bladder cancer." (PMID 29069865, 2017). "S100A4 is a calcium binding protein implicated in metastasis, and while it is well-studied in bladder cancer, there are mixed reports of its prognostic value." (PMID 29207636, 2017). "We showed that down-regulation of ANXA10 caused up-regulation of S100A4 in the SW780 bladder cancer cell line." (PMID 21979422, 2011). "Our study indicates an association between expression levels of ANXA10 and S100A4 in bladder cancer." (PMID 21979422, 2011). "Furthermore, DNA methylation has been found to be partially and variably involved in S100A4 expression in bladder cancer that is associated with moderate CpG-content hypomethylation." (PMID 29069865, 2017). "S100A4 mediated miR-149-3p-induced anti-metastatic effects of bladder cancer cells in vitro and in vivo." (PMID 32842846, 2020). "S100A4 is overexpressed in multiple cancers such as breast, lung, colorectal, esophageal, gastric, pancreatic, hepatocellular, gallbladder, and bladder cancers." (PMID 31881983, 2019). "In the present study, we demonstrate that S100A4 is up-regulated in MB49 bladder cancer stem cells (MCSCs)." (PMID 30045697, 2018). "In comparison with normal urothelium, most of the bladder cancer tissues show highly expression of S100A4, especially in invasive bladder cancer present in the invasive regions and in single infiltrating cells." (PMID 29069865, 2017). "Urothelial cells treated with bladder cancer exosomes showed an increased expression in several mesenchymal markers, including α-smooth muscle actin, S100A4 and snail, as compared with phosphate-buffered saline (PBS)-treated cells." (PMID 26280654, 2015). "We showed that down-regulation of ANXA10 in a bladder cancer cell line (SW780) resulted in up-regulation of S100A4." (PMID 21979422, 2011). "miR-149-3p inhibits bladder cancer proliferation, migration, and invasion targeting S100A4." (PMID 35719192, 2022). "miR-149-3p by targeting S100A4 could inhibit proliferation, migration, and invasion of bladder cancer." (PMID 35317077, 2022). "Moreover, it has been observed that S100A4 can enhance the proliferation capacity of bladder cancer stem cells." (PMID 33805347, 2021). "Therefore, new strategies targeting bladder CSCs are needed and the aim of this study was to investigate the effect of S100A4 on the proliferation capacity of MB49 bladder cancer stem cells (MCSCs)." (PMID 30045697, 2018). "Additionally, miR-149-3p inhibits the proliferation, migration, and invasion of bladder cancer cells by targeting the S100A4 protein, which is involved with cellular differentiation, motility, and regulating transcription." (PMID 29543730, 2018). "Up-regulation of S100A4 in an invasive but non-metastatic rat bladder cancer cell line generates metastatic variants." (PMID 21979422, 2011). "Furthermore, strong focal staining of S100A4 has been shown to act as prognostic marker for metastatic disease in bladder cancer." (PMID 21979422, 2011). "S100A4 was found to be overexpressed in bladder cancer and could be served as a predictor of tumor progression." (PMID 18793447, 2008). "It was found that regulators of cell cycle and cell proliferation such as S100A4, CCND2, C13ORF15 (RGCC), and SYK and genes associated with glucose or ion transport such as SLC2A3 and TMEM16A (ANO1) were upregulated in the persistently infected bladder cancer cells." (PMID 34044804, 2021).
bladder cancer (continued). "miR-149-3p binds to S100A4 mRNA and reduces its levels, thereby inhibiting S100A4-induced EMT in bladder cancer cells." (PMID 38396852, 2024). "EVs from bladder cancer cells were able to induce the migration of urothelial cells by downregulating the expression of the epithelial markers E-cadherin and β-catenin and inducing the expression of mesenchymal genes (alpha-smooth muscle actin or α-SMA and S100 calcium-binding protein A4 or S100A4)." (PMID 37760395, 2023).
ovarian carcinoma (22 papers, 2012 to 2025). A malignant neoplasm originating from the surface ovarian epithelium. "Expression of S100A4 has been shown to be increased in ovarian cancer in association with clinical stage of these patients." (PMID 35317077, 2022). "In patients with ovarian cancer, high circulating S100A4 transcript levels are associated with shorter progression‐free survival and overall survival, making it a potential prognostic biomarker for ovarian cancer." (PMID 33828176, 2021). "We report that high MACC1 and S100A4 transcript levels at primary diagnosis of ovarian cancer are associated with advanced disease and predict poor prognosis." (PMID 30927479, 2019). "Level of nuclear S100A4 expression is associated with advanced tumor stage, chemoresistance, and poor prognosis of ovarian cancer." (PMID 29069865, 2017). "S100A4 overexpression was associated with advanced TNM stages of ovarian cancer." (PMID 29069865, 2017). "Down-regulation of this CBP has reduced the mobility of ovarian cancer cells and their metastatic ability, while up-regulation of S100A4 has increased the invasive aptitude of these cells." (PMID 35317077, 2022). "Conclusively, circulating MACC1 and S100A4 transcripts are significantly elevated in serum of ovarian cancer patients and show a high correlation in the course of surgery and chemotherapy, which is mostly independent from CA125 serum levels." (PMID 30927479, 2019). "MACC1 and S100A4 transcripts were quantified in a total of 318 serum samples from 79 ovarian cancer patients by RT‐qPCR and digital droplet PCR, respectively." (PMID 30927479, 2019). "MACC1 and S100A4 transcripts were significantly elevated in serum of ovarian cancer patients, compared to healthy controls (P = 0.024; P < 0.001)." (PMID 30927479, 2019). "For the first time, we systematically tracked circulating serum levels of MACC1 and S100A4 transcripts in the course of surgery and chemotherapy and analyzed their clinical relevance for ovarian cancer." (PMID 30927479, 2019). "We encourage further investigation, considering MACC1 and S100A4 as a potential therapeutic target for ovarian cancer." (PMID 30927479, 2019). "Nevertheless, despite a very recent preliminary study, investigating clinical relevance of S100A4 protein in serum, this is the first study on MACC1 and S100A4 serum transcripts in ovarian cancer." (PMID 30927479, 2019). "In the present liquid biopsy approach, we systematically analyzed clinical relevance of circulating MACC1 and S100A4 transcripts in ovarian cancer patients." (PMID 30927479, 2019). "In contrast to MACC1, S100A4 levels in serum of ovarian cancer patients showed only a small overlap to healthy controls, resulting in a good discrimination between ‘ovarian cancer’ and ‘healthy’ (AUC = 0.81)." (PMID 30927479, 2019). "Our data harmonize with the previously shown oncogenic and metastasis‐initiating impact of MACC1 and S100A4 and extend our knowledge of these genes to innovative liquid biopsy approaches for ovarian cancer." (PMID 30927479, 2019). "Collectively, high circulating MACC1 and S100A4 levels in serum of ovarian cancer patients correlate with advanced disease and predict suboptimal primary debulking surgery without achieving macroscopically complete tumor resection." (PMID 30927479, 2019). "We observed that serum levels of both, MACC1 and S100A4, are significantly upregulated at primary diagnosis of ovarian cancer, compared to healthy controls." (PMID 30927479, 2019). "We analyzed the levels of serum MACC1 and S100A4 transcripts in a cohort of clinically documented ovarian cancer patients at primary diagnosis (n = 77) and compared it to the levels in serum of healthy controls (n = 25)." (PMID 30927479, 2019). "Compared to MACC1, S100A4 levels allow superior discrimination between ovarian cancer patients and healthy controls." (PMID 30927479, 2019).
ovarian carcinoma (continued). "Ovarian cancer cells can express cytoplasmic and nuclear S100A4, however, myofibroblasts in ovarian cancer lesions express only cytoplasmic S100A4." (PMID 29069865, 2017). "Ovarian cancer cells express high levels of S100A4 mRNA and protein to increase tumor cell invasiveness and for the upregulation of RhoA activity." (PMID 29069865, 2017). "S100A4 expression in stromal cells has been reported to be higher in metastatic than in primary ovarian cancer." (PMID 29069865, 2017). "S100A4, which plays an important role in the aggressiveness of ovarian carcinoma cells, was detected in 3 out of 20 allogenic sera." (PMID 22684412, 2012). "Moreover, elevated levels of S100A4 were linked to hypomethylation of CpG sites in the first intron of S100A4 in cisplatin-resistant ovarian carcinoma cells." (PMID 38413011, 2024). "Furthermore, the efficacy of the anti-S100A4 antibody drug in suppressing the metastatic ability of malignant tumors in other organs, including ovarian cancer, has been investigated." (PMID 35723396, 2022). "Future studies will have to address, whether the circulating S100A4 transcript level could be used as a blood‐based screening marker for ovarian cancer." (PMID 30927479, 2019). "Furthermore, we encourage future translational investigations with MACC1 and S100A4 as therapeutic targets for ovarian cancer." (PMID 30927479, 2019). "Our data now extend our knowledge on MACC1 and S100A4 to ovarian cancer." (PMID 30927479, 2019). "Oncogenic function of MACC1 and S100A4 has likewise been proposed for ovarian cancer." (PMID 30927479, 2019). "Moreover, exposure of ovarian cancer cells to hypoxia was found to reduce the methylation level of S100A4 first intron that was shown to bind to HIF-1α, thereby enhancing ovarian cancer cell invasiveness and its metastasis potential." (PMID 29069865, 2017). "In addition to RAB25 amplification, rearrangements and increased expression of the S100A4 gene have been correlated with advanced disease stages and poor survival in other malignancies, such as ovarian osteosarcoma metastasis and ovarian carcinoma." (PMID 23825676, 2013). "Therefore, the highly concordant dynamics of MACC1 and S100A4 transcripts in serum of ovarian cancer patients could be explained by a proportional release upon apoptosis or by a possibly co‐regulated active secretion." (PMID 30927479, 2019). "However, clinical relevance of MACC1 and S100A4 transcripts as potential blood‐based biomarkers for ovarian cancer patients is completely unknown." (PMID 30927479, 2019). "In ovarian cancer, resistant subpopulations exhibiting high ALDH1A1 and S100A4 expression were found to co-localize with lactylation signals, linking metabolic reprogramming directly to spatial stemness niches." (PMID 41583433, 2025). "This is the first study in ovarian cancer to propose circulating MACC1 and S100A4 transcripts as potential liquid biopsy markers." (PMID 30927479, 2019). "In particular, increased expression of S100A1, S100A4, S100A7, and S100A14 has been documented in multiple cancers including ovarian cancer." (PMID 31739800, 2019). "In ovarian cancer, many S100 family members have been reported, such as S100A1, S100A4, S100A6, S100B and S100P." (PMID 30558666, 2018). "S100A4 was upregulated by hypoxia in ovarian cancer, with reduced methylation of the HRE in S100A4’s promoter regions and increased binding of HIF1." (PMID 25079072, 2014). "Further studies are necessary to investigate the role of S100A4 in the interaction between HE4 and ANXA2 in ovarian cancer cells." (PMID 25362534, 2014). "We conclude that high levels of circulating MACC1 or S100A4 transcripts at primary diagnosis (but not among follow‐up samples during surgery and adjuvant chemotherapy) are unfavorable prognostic factors for ovarian cancer patients and indicate poor prognosis." (PMID 30927479, 2019).
ovarian carcinoma (continued). "In the areas of breast and ovarian cancer, CAF subtypes have been defined based on multicolor flow cytometry yielding the four subtypes depending on how they stained for the fibroblast markers FAP, CD29, αSMA, S100-A4, PDGFRβ, and CAV1, accumulating differently in different tumors." (PMID 37745296, 2023). "Since we found that levels of MACC1 and S100A4 transcripts at primary diagnosis correlated with FIGO stage, we suggest that a significant proportion of MACC1 and S100A4 transcripts is derived from ovarian cancer cells and reflects the patient's individual tumor load." (PMID 30927479, 2019).
rheumatoid arthritis (20 papers, 2013 to 2025). A chronic, systemic autoimmune disorder characterized by inflammation in the synovial membranes and articular surfaces. "S100A4 expression has been associated with chronic inflammatory conditions such as fibrosis, rheumatoid arthritis (RA), allergic asthma and dermatitis." (PMID 40078995, 2025). "Recently, S100A4 has been implicated in the progression of fibrosis in various organs and in inflammatory diseases such as rheumatoid arthritis." (PMID 40718484, 2025). "Previous studies have demonstrated the roles of calgranulins and S100A4 in the pathogenic process of several autoimmune disorders including rheumatoid arthritis, inflammatory bowel diseases, and others." (PMID 23922901, 2013). "Moreover, as the elevated expression of S100A4 has been implicated in the pathology of tissue fibrosis, rheumatoid arthritis and other types of cancer, a wide application of therapeutics against S100A4 may be expected." (PMID 33549040, 2021). "We and others found local or systemic up-regulation of S100A4 in rheumatoid arthritis (RA), psoriatic arthritis, idiopathic inflammatory myopathies or in systemic sclerosis and showed its association with disease severity." (PMID 32021963, 2020). "Monocytes activated by extracellular S100A4 produced inflammatory cytokines which lead to aggravated disease activity of rheumatoid arthritis." (PMID 32307910, 2020). "The expression levels of S100A4 increase in rheumatoid arthritis, osteoarthritis, psoriasis, idiopathic inflammatory myopathies, inflammatory bowel diseases like Crohn's disease, cardiac hypertrophy, hepatic hemangiomas, and autoimmune diseases." (PMID 30111999, 2018). "The levels of the bioactive form of S100A4 are correlated with its disease activity, and thus S100A4 is successfully decreased by blocking therapy in rheumatoid arthritis patients." (PMID 29204268, 2017). "S100A4 expression is also known to be involved in the pathogenesis of several autoimmune diseases, such as rheumatoid arthritis, systemic sclerosis, and psoriasis." (PMID 29204268, 2017). "S100A4 proteins are expressed in various diseases, including cancer, vascular disorders, rheumatoid arthritis, and pulmonary disorders; and S100A4 was found to be up-regulated after cardiac infarction and neural injury." (PMID 27559743, 2016). "In rheumatoid arthritis, an active feedback loop between inciting macrophages/leukocytes and synovial fibroblasts has been proposed in which S100A4 acts in an autocrine/paracrine manner to amplify matrix degradation and apoptosis, primarily through secretion of matrix metalloproteinases (MMPs)." (PMID 37090702, 2023). "Clinically oriented research on S100A4 has been largely focused on its cancer metastasis-promoting properties, and its role in promoting pathological inflammation in rheumatoid arthritis, cardiovascular disease, fibrotic diseases, and experimental autoimmune encephalomyelitis." (PMID 28951732, 2017). "Furthermore, therapy targeting S100A4 can suppress the progression of rheumatoid arthritis and persistent high S100A4 expression will predict poor treatment outcome of rheumatoid arthritis." (PMID 29204268, 2017). "Moreover, we have previously found increased circulating levels of S100A4 in patients with rheumatoid arthritis (RA) in comparison with control individuals and demonstrated a positive correlation between S100A4 and disease activity in RA." (PMID 25359220, 2014). "S100A4 is involved in promoting cancer progression and metastasis, fibrosis, inflammation, immune response, neuroprotection, angiogenesis, and some common non-tumor diseases including being upregulated in cells infiltrating rheumatoid arthritis synovial tissue." (PMID 32687504, 2020). "Further, S100A4 or fibroblast-specific protein 1 (FSP-1) is a molecule with cellular expression and release at sites of joint destruction in rheumatoid arthritis, whereby extracellular S100A4 has been shown to increase the expression of MMP-3." (PMID 34204207, 2021).